MYCBP2 (MYC binding protein 2)
Diseases named in the same sentence as MYCBP2 in open-access papers:
MYCBP2 is named in the same sentence as 49 diseases in open-access papers, as found by Europe PMC text mining. Sharing a sentence is not in itself a finding about the gene and the disease. The quoted sentences say what the papers report.
autism (6 papers, 2013 to 2025). Persistent deficits in social interaction and communication and interaction as well as a markedly restricted repertoire of activity and interest as well as repetitive patterns of behavior. "used machine learning methods based on random forest and found two autism genes: MYC Binding Protein 2 and Phosphatase and Tensin Homolog genes." (PMID 40297334, 2025). "In turn, the rest-induced E3 ubiquitin ligase MYCBP2 reportedly cooperates with ROBO2 in the olfactory system development in mice and is associated with neurodevelopmental problems and autism in humans." (PMID 40725218, 2025). "Patients with MYCBP2 variants have a neurodevelopmental disorder called MDCD that features corpus callosum defects and a spectrum of neurobehavioral deficits including developmental delay, intellectual disability and autism." (PMID 39671436, 2024). "This includes a study that examined the MYCBP2 locus in 300 autism patients." (PMID 27008623, 2016). "Since mounting evidence has established autism as a disorder of the synapses, we tested whether rare genetic variants in TSC1, TSC2, MYCBP2, RHEB and FBXO45, genes that regulate mTORC1 signaling and/or play a role in synapse development and function, contribute to the pathogenesis of idiopathic ASD." (PMID 23514105, 2013).
acute lymphoblastic leukemia (2 papers, 2015 to 2021). Leukemia with an acute onset, characterized by the presence of lymphoblasts in the bone marrow and the peripheral blood. "A study reported that low MYCBP2 expression was associated with high-risk acute lymphoblastic leukemia (ALL)." (PMID 34946806, 2021).
colon cancer (2 papers, 2018 to 2024). "Another novel discovery is the identification of MYCBP2 as a coding-gene target of miR-1247 for colon cancer." (PMID 30318507, 2018). "DNA hypermethylation plays a crucial role in this subtype of colon cancer by suppressing miR-1247 expression, which results in an increase in MYCBP2 and its downstream c-myc protein, thereby leading to tumour development." (PMID 30318507, 2018). "miR-1247 acts as a tumour suppressor by inhibiting MYCBP2 in methylator colon cancer." (PMID 30318507, 2018). "Collectively, these data suggest that MYCBP2 is a miR-1247 target and the miR-1247/MYCBP2/c-myc axis may serve as a tumour suppressive pathway in methylator colon cancers." (PMID 30318507, 2018). "Therefore, MYCBP2 is a miR-1247 target with predominance in methylator colon cancer cells." (PMID 30318507, 2018). "Knowing that MYCBP2 expression is inversely correlated with miR-1247 in vitro, this relationship was then studied in five cryosections of hypermethylated and non-methylated patient colon cancers that were stained for MYCBP2 expression by immunohistochemistry." (PMID 30318507, 2018).
Developmental delay (2 papers, 2024). "Importantly, the biomedical relevance of our findings are heightened by a recent study that identified genetic variants in MYCBP2, which cause a neurodevelopmental disorder termed MYCBP2-related Developmental delay with Corpus callosum Defects (MDCD)." (PMID 38289221, 2024). "MYCBP2 (also called Phr1 in rodents) is an evolutionarily conserved regulator of axon development, and genetic variants in MYCBP2 were recently shown to cause a neurodevelopmental spectrum disorder called MYCBP2-related developmental delay with corpus callosum defects (MDCD)." (PMID 39671436, 2024).
leukemia (2 papers, 2015 to 2024). A malignant (clonal) hematologic disorder, involving hematopoietic stem cells and characterized by the presence of primitive or atypical myeloid or lymphoid cells in the bone marrow and the blood. "Reduced expression of the MYCBP2 gene has previously been observed in leukemia patients, which has been revealed that CK2 inhibitor takes the anti-leukemia effect through Ikaros-mediated regulation on MYCBP2 expression in high-risk leukemia." (PMID 39222712, 2024). "We found c-MYC expression is negatively correlated with MYCBP2 expression in ALL; and high c-MYC expression and/or low MYCBP2 expression is associated with high-risk leukemia." (PMID 26517351, 2015). "High c-MYC and/or low MYCBP2 or low Ikaros expression is correlated with high-risk leukemia." (PMID 26517351, 2015). "MYC binding protein 2 (MYCBP2) is a probable E3 ubiquitin ligase and its function in leukemia is unknown." (PMID 26517351, 2015). "Our data reveals the oncogenic effect of an Ikaros/MYCBP2/c-MYC axis in adult ALL, and suggests a mechanism by which CK2 inhibitors exert their anti-leukemia effect." (PMID 26517351, 2015). "Therefore, our data suggests that CK2 inhibitors exert their anti-leukemia effect through Ikaros-mediated suppression of c-MYC expression and activation of MYCBP2 expression." (PMID 26517351, 2015).
Obesity (2 papers, 2022 to 2024). Accumulation of substantial excess body fat. "Herein, we focused on purified preadipocytes and have elucidated the anti-obesity role of ANXA1, PDLIM7 and MYCBP2 in the suppression of adipogenesis, along with the underlying molecular mechanisms." (PMID 39174522, 2024).
oral squamous cell carcinoma (2 papers, 2023 to 2024). "Gene knockout assays have shown that RGS12 can inhibit the progression of oral squamous cell carcinoma by controlling the polarization of M1 in TAMs by controlling ciliated MYCBP2/KIF2A signaling." (PMID 38688945, 2024).
schizophrenia (2 papers, 2011 to 2015). A major psychotic disorder characterized by abnormalities in the perception or expression of reality. "The other YWHAZ abnormalities were the interactions with RNPS1 and LGALS1 in schizophrenia; the interactions with MYCBP2, PRDX1 or TP1l in bipolar disorder; the interactions with RPLP2 and VIM in major depression; and the interactions with RPLP0 in both schizophrenia and major depression." (PMID 22373040, 2011).
T-cell lymphoma (2 papers, 2018 to 2021). "MYCBP2, a member of the c-myc oncogene family, was overexpressed in T-cell lymphoma with a poor prognosis." (PMID 34946806, 2021).
tauopathies (2 papers, 2025). "Both TRIM21 and MYCBP2 are abundant forms of E3 ligases, although their roles in tauopathies remain obscure." (PMID 39974971, 2025). "Whether and how HERC1, PJA2, and MYCBP2 participate in tauopathy and mediate the protective effect of sorafenib requires further scrutiny." (PMID 41311387, 2025).
thyroid cancer (2 papers, 2022 to 2025). "In thyroid cancer (TC), MYC binding protein 2 (MYCBP2) has been linked to inflammatory cell infiltration and patient survival." (PMID 41287790, 2025).
angioimmunoblastic T-cell lymphoma (1 paper, 2015). A mature T-cell non-Hodgkin lymphoma, characterized by systemic disease and a polymorphous infiltrate involving lymph nodes and extranodal sites. "Additionally, it is reported that MYCBP2 is a candidate for the transformation-associated gene that maps to the 13q22.3 locus in Angioimmunoblastic T-cell lymphoma (AITL)." (PMID 26517351, 2015).
Cirrhosis (1 paper, 2025). A chronic disorder of the liver in which liver tissue becomes scarred and is partially replaced by regenerative nodules and fibrotic tissue resulting in loss of liver function. "From gene-level testing, the risk genes APOB and MYCBP2 were positively associated with serum liver enzymes, LiverRisk score, cirrhosis, and type 2 diabetes." (PMID 40065360, 2025).
colorectal cancer (1 paper, 2021). A primary or metastatic malignant neoplasm that affects the colon or rectum. "MYCBP2 mRNA expression was negatively correlated with survival in colorectal cancer (CRC)." (PMID 34946806, 2021).
Hepatic steatosis (1 paper, 2025). Steatosis is a term used to denote lipid accumulation within hepatocytes. "MYCBP2 inhibits signaling pathways that drive hepatic steatosis, including mTOR and p38 MAPK, while also suppressing adipogenesis by promoting SMAD4 ubiquitination, possibly explaining why aggregated deleterious variants in MYCBP2 were positively associated with both MASLD and body fat percentage." (PMID 40065360, 2025).
liver fibrosis (1 paper, 2025).
lymphoma (1 paper, 2015). A malignant (clonal) proliferation of B- lymphocytes or T- lymphocytes which involves the lymph nodes, bone marrow and/or extranodal sites. "The region in MYC, which is responsible for MYCBP2 interaction, is frequently mutated in Burkitt's and AIDS-associated lymphomas, indicating MYCBP2 suppress MYC activity." (PMID 26517351, 2015).
melanoma (1 paper, 2022). A malignant, usually aggressive tumor composed of atypical, neoplastic melanocytes. "Next, we used the ICI-treated melanoma and urothelial cohorts to further verify the relationship between MYCBP2 expression and prognosis in ICI-treated patients." (PMID 36582246, 2022).
muscle atrophy (1 paper, 2014). The loss of muscle tissue due to inactivity or disease. "We focused this analysis on four genes that are closely linked to muscle atrophy (MSTN) and fast‐twitch, glycolytic muscle properties (ANKRD1, MYH8 and MYCBP2)." (PMID 24744911, 2014).
oral cancer (1 paper, 2023). "However, downregulation of RGS12 in oral cancer inhibits the MYCBP2 activity, which further causes decreased ciliogenesis, increased M2 TAMs polarization, and promotes oral cancer growth." (PMID 36797232, 2023). "Upregulation of RGS12 activates phosphorylation of MYCBP2 to enhance ciliogenesis by degrading KIF2A and promotes the M1 TAMs polarization to further eliminate oral cancer cells." (PMID 36797232, 2023). "In this study, by investigating the roles of RGS12 on TAMs from mice with oral cancer, we revealed that RGS12 is an essential factor to control immune activation in oral cancer by regulating macrophage polarization and ciliogenesis via MYCBP2/KIF2A." (PMID 36797232, 2023). "Given that macrophage RGS12 is important for oral cancer development, targeting the RGS12/MYCBP2 pathway may be an attractive therapeutic avenue in this disease." (PMID 36797232, 2023).
pneumonia (1 paper, 2018). An acute, acute and chronic, or chronic inflammation focally or diffusely affecting the lung parenchyma, caused by an infection in one or both of the lungs (by bacteria, viruses, fungi, or mycoplasma.). "Simultaneously, based on target gene prediction and qRT-PCR analysis, we found that genes MYCBP2, UBE2V2, and UBE2D2 may play important roles in viral replication and Adv-induced pneumonia." (PMID 30405317, 2018).
preeclampsia (1 paper, 2019). Preeclampsia is a hypertensive disorder of pregnancy that is characterized by new-onset hypertension with proteinuria presenting after 20 weeks of gestation, and depending on mild or severe forms may initially present with severe headache, visual disturbances, and hyperreflexia. "Interestingly, MYCBP2 which was identified as a candidate gene for gestation length in the LM population was previously proposed as a candidate gene for preeclampsia within European humans." (PMID 31749838, 2019).
Splenomegaly (1 paper, 2015). Abnormal increased size of the spleen. "The percentage of patients exhibiting splenomegaly and liver infiltration was significantly higher in the low MYCBP2 expression group than in the high expression group (54.3% vs 35.9%, P = 0.033; 35.7% vs 15.4%, P = 0.007)." (PMID 26517351, 2015). "Patients with high c-MYC expression and/or low MYCBP2 expression had higher WBC counts and a higher percentage of CD34+ or CD33+ cells, as well as splenomegaly, liver infiltration, higher BM blasts, and lower CR rate." (PMID 26517351, 2015).
tumor (11 papers, 2018 to 2026). "We further investigated if the inhibition of MYCBP2 expression by miR-1247 impacted the tumour associated transcriptional factor c-myc." (PMID 30318507, 2018). "MYCBP2 may also be involved in the regulation of signaling pathways associated with anti-tumor immune responses or the production of inflammatory factors." (PMID 36582246, 2022). "The MYCBP2/c-myc axis may underlie the anti-tumour activities of miR-1247 and is a potential therapeutic target via demethylation agents." (PMID 30318507, 2018). "The MYCBP2/c-myc axis may underlie the anti-tumor activities of miR-1247." (PMID 32854257, 2020). "In vivo studies demonstrated that MYCBP2 knockdown significantly reduced tumor growth and enhanced apoptosis in a xenograft model." (PMID 42036047, 2026). "RGS12 enhances the phosphorylation of Myc-binding protein 2 (MYCBP2) to degrade the ciliary protein KIF2A and cilia disassembly, which promotes tumor-associated macrophage polarization into M2 macrophages." (PMID 40271194, 2025). "Although the molecular mechanism of the positive regulation of c-myc by MYCBP2 remains unknown, these data demonstrate that miR-1247 directly targets MYCBP2, and is associated with decreased expression of c-myc, which may account for the tumour suppressive function of miR-1247." (PMID 30318507, 2018). "In the current study, we have characterised its function as a novel tumour suppressor and identified MYCBP2 as its downstream target." (PMID 30318507, 2018). "Pathway enrichment analysis showed that MYCBP2 may be involved in anti-tumor immune responses." (PMID 36582246, 2022). "MYCBP2, AFF2, and C3 influenced patient outcomes by affecting tumor growth, metastasis, and treatment resistance." (PMID 40729021, 2025). "From this study, proteins of interest identified by tandem MS-MS that were decreased in sera from tumor-bearing rats treated with OKN-007, compared to untreated, included ABCA2, ATP5B, CNTN2, ITGA3, KMT2D, MYCBP2, NOTCH3, and VCAN." (PMID 35053843, 2022). "Proteins of interest identified by tandem MS-MS that were decreased in sera from tumor-bearing rats that were either OKN-007-treated or untreated included ABCA2, ATP5B, CNTN2, ITGA3, KMT2D, MYCBP2, NOTCH3, and VCAN." (PMID 35053843, 2022). "Previous reports have shown that miR-92a-3p has multiple target genes, most of which are tumor suppressors, including PTEN, MYCBP2, FBXW7 and so on." (PMID 34082648, 2021). "Higher MYCBP2 mRNA levels correlated with a worse survival in CRC patients, which underscores the potential relevance of miR-1247 as a tumour suppressor with effects on MYCBP2." (PMID 30318507, 2018).
cancer (7 papers, 2010 to 2025). A tumor composed of atypical neoplastic, often pleomorphic cells that invade other tissues. "Although prior research has linked mutations or dysregulation of MYCBP2 with various disorders, such as neurodegenerative diseases and cancers, its specific functions in the CNS, especially in the modulation of microglial polarization following SCI, have not been fully elucidated." (PMID 38896802, 2024). "In TC, Myc binding protein 2 (MYCBP2) is correlated with inflammatory cell infiltration and cancer prognosis." (PMID 36582246, 2022). "The MYC binding protein 2 (MYCBP2) was found to be a binding partner for the epidermal growth factor receptor (EGFR), which is frequently mutated in various cancers." (PMID 35053843, 2022).
neurodevelopmental disorder (6 papers, 2015 to 2026). A behavioral and cognitive disorder with onset during the developmental period that involves impaired or aberrant development of intellectual, motor, or social functions. "In the initial study describing MYCBP2-associated neurodevelopmental disorder, all individuals had de novo heterozygous pathogenic variants." (PMID 41543631, 2026). "Here we present the case of a proband with a maternally inherited MYCBP2-associated neurodevelopmental disorder." (PMID 41543631, 2026). "MYCBP2-associated neurodevelopmental disorder is a relatively newly described autosomal dominant genetic disorder." (PMID 41543631, 2026). "RPM-1 and its human homolog MYCBP2 are prominent evolutionarily conserved regulators of nervous system development and associated with a neurodevelopmental disorder." (PMID 39671436, 2024). "C. elegans RPM-1 is orthologous to human MYCBP2, a prominent player in nervous system development recently associated with a neurodevelopmental disorder." (PMID 39671436, 2024). "We describe here the first case of an inherited MYCBP2-associated neurodevelopmental disorder in a pediatric patient inherited from a less-affected parent, expanding the phenotype of this neurodevelopmental disorder to include isolated mild executive dysfunction." (PMID 41543631, 2026). "Trio whole exome sequencing was significant for a maternally inherited heterozygous pathogenic variant in MYCBP2 (NM_015057.4), c.4409dup (p.Leu1470Phefs*7) resulting in a diagnosis of MYCBP2-related neurodevelopmental disorder." (PMID 41543631, 2026). "Our findings are particularly intriguing, given the causal genetic link between MYCBP2/RPM-1 and a neurodevelopmental disorder." (PMID 39671436, 2024). "Importantly, other ubiquitin ligase signaling hubs associated with childhood neurodevelopmental disorders, such as RPM-1 (MYCBP2) and EEL-1 (HUWE1), also utilize both ubiquitin ligase activity and ligase-independent mechanisms to shape neuron development and function 51,52." (PMID 40766417, 2025).
brain disorder (2 papers, 2020 to 2024). A disease affecting the brain or part of the brain. "Four genes, ZYG11B, HECTD1, CAND1, and MYCBP2, ranked second, fourth, seventh and tenth, are all involved in protein ubiquitination, which has been implicated in neuronal function and brain disorders, including ASD." (PMID 33133139, 2020). "Thus, our findings orthogonally validate the adhesome using an organismal setting, identify an adhesome axis that inhibits RPM-1 (MYCBP2), and highlight important new links between the adhesome and brain disorders." (PMID 39671436, 2024).
MYCBP2 also shares sentences with these, for which no sentence is quoted: infection (3 papers); breast carcinoma (2); MYCBP2-related developmental delay with corpus callosum defects (2); neurodegenerative disease (2); acute leukemia (1); acute myeloid leukemia (1); aspergillosis (1); bipolar disorder (1); candidiasis (1); ciliopathy (1); glioma (1); hyperlipidemia (1); Intellectual disability (1); major depression (1); myelogenous leukemia (1); pancreatic cancer (1); Pectobacterium carotovorum infection (1); prostate carcinoma (1); spinal cord injury (1); steatosis (1); tuberous sclerosis (1); type 2 diabetes (1).